PRDM5 (PR/SET domain 5)
Diseases named in the same sentence as PRDM5 in open-access papers (continued):
Sharing a sentence is not in itself a finding about the gene and the disease.
colorectal cancer (3 papers, 2015 to 2022). A primary or metastatic malignant neoplasm that affects the colon or rectum. "Recent studies indicated that high levels of PRDM5 are associated with better outcomes for glioma and colorectal cancer." (PMID 35799142, 2022). "A publicly available database was searched for presence of PRDM5 mutations in colorectal cancer." (PMID 25613750, 2015). "Of 295 colorectal cancers, PRDM5 was mutated in only 6 (2%) cancers which were all BRAF wild type." (PMID 25613750, 2015). "CHIP sequencing of colorectal cancer cell lines found that the response genes Adamts9, Col1a1, Mmp13 and Mgll in PRDM5 have been confirmed strongly regulated by PRDM5." (PMID 35799142, 2022). "Despite several cancers identified as having frequent PRDM5 promoter methylation, only minimal rates of methylated PRDM5 has been found in an uncharacterized series of colorectal cancers." (PMID 25613750, 2015). "Overall, this investigation highlights PRDM5 as an important tumour suppressor gene in colorectal cancer." (PMID 25613750, 2015). "This is the first study that has analysed the rate of PRDM5 methylation and protein expression in a large and well characterized series of colorectal cancer and polyp subgroups." (PMID 25613750, 2015). "This study investigated a large series of molecularly subtyped colorectal cancers and precursor lesions for the presence of PRDM5 methylation and protein expression." (PMID 25613750, 2015). "Serrated pathway colorectal cancers demonstrated early and progressive PRDM5 methylation with advancing disease." (PMID 25613750, 2015). "We believe that in the future, PRDM5 methylation may also become part of cancer screening, and there is a blood-based screening for DNA methylation markers in colorectal cancer, we showed that epigenetic therapy of PRDM5 is achievable." (PMID 35799142, 2022). "This study has investigated whether PRDM5 methylation is a target of epigenetic silencing more commonly in the serrated compared to the traditional pathway of colorectal cancer." (PMID 25613750, 2015). "This frequent loss of PRDM5 protein expression seen by immunohistochemistry is concordant with findings of a previous study that investigated expression in 18 colorectal cancers that were not molecularly subtyped." (PMID 25613750, 2015). "PRDM5 is located on chromosome 4q27 which is within a region commonly deleted in colorectal cancer." (PMID 25613750, 2015). "PRDM5 methylation is also an early event in the occurrence and development of BRAF mutant colorectal cancer." (PMID 35799142, 2022). "PRDM5 has not been extensively investigated in specific subtypes of colorectal cancers." (PMID 25613750, 2015). "It was found that the colorectal cancer cell line, SW480, lacked PRDM5 expression due to methylation of histone H3K27 and not as a result of a methylated promoter region." (PMID 25613750, 2015).
glioma (3 papers, 2015 to 2022). A benign or malignant brain and spinal cord tumor that arises from glial cells (astrocytes, oligodendrocytes, ependymal cells). "In another research, PRDM5 expression levels in glioma specimens were low and correlated with clinicopathological parameters and poor prognosis." (PMID 35799142, 2022). "Silencing PRDM5 alone can reduce the apoptosis of glioma cells and intestinal epithelial cells." (PMID 35799142, 2022). "This is due to there being a considerable presence of PRDM5 methylation and transcript down-regulation in several non-CIMP cancer types, and there is a lack of reported PRDM5 methylation in other CIMP related cancers such as glioma." (PMID 25613750, 2015).
keratoconus (3 papers, 2013 to 2023). A degenerative, structural disorder of the eye, characterized by a cone-shaped protrusion of the cornea. "Heterozygous carriers of PRDM5 mutations have mildly reduced central corneal thickness, mild keratoconus, and blue sclera compared to individuals with homozygous mutations, who have more severe features." (PMID 26489929, 2016). "Variants in the PRDM5 gene were previously identified in anterior segment defects, i.e., autosomal recessive brittle cornea syndrome and keratoconus." (PMID 26489929, 2016). "In BCS patients carrying PRDM5 mutations, a relationship was noted between the zygosity of the mutation (homozygous/heterozygous) and the clinical features of the patients and age of onset of keratoconus." (PMID 26489929, 2016). "Notable phenotypic features including blue sclera, keratoconus, deafness, and joint hypermobility are present, with the suggested mechanism being a result of PRDM5′s role in extracellular matrix homeostasis." (PMID 37629506, 2023). "A recent study proposed that heterozygous variants in PRDM5 and ZNF469 predisposed the patients toward the development of isolated keratoconus." (PMID 26489929, 2016). "Previously, variants in the PRDM5 gene have been identified in autosomal recessive brittle cornea syndrome (BCS), and an enrichment of potentially pathogenic heterozygous variants has been observed in keratoconus." (PMID 26489929, 2016).
liver cancer (3 papers, 2015 to 2020). An epithelial or non-epithelial malignant neoplasm that arises from the liver. "This association was also seen in a previous study where PRDM5 methylation was more common in high grade breast and liver cancers." (PMID 25613750, 2015). "PRDM5 is silenced in human breast, ovarian, and liver cancers by CpG island methylation of its promoter region." (PMID 32290321, 2020). "Finally, epigenome and transcriptome profiling of mouse primary liver cancer identified Tbx3 and Prdm5 as major microenvironment-dependent and epigenetically regulated lineage-commitment factors, a function that is conserved in humans." (PMID 32290321, 2020).
neutropenia (3 papers, 2009 to 2015). A decrease in the number of neutrophils found in the blood. "Neutropenia-associated PRDM5 sequence variants interfere with its transcriptional activity." (PMID 24832654, 2013). "PRDM5 is in fact able to interact with Growth factor independent 1 (Gfi1) transcription factor, essential for hematopoiesis, whose inactivation impaired blood cell formation, causing neutropenia and lymphopenia and release from bone marrow of immature cells." (PMID 24832654, 2013). "PRDM5 may also have other disease-linked functions: two PRDM5 sequence variants were recently found in a study of neutropenic patients that lacked mutations in genes associated to hereditary neutropenia, such as ELA2 and GFI1." (PMID 19169355, 2009).
aneurysm (2 papers, 2023 to 2024). Bulging or ballooning in an area of an artery secondary to arterial wall weakening. "We hypothesize that if a genetic variation in PRDM5 encodes for an aberrant protein, a subsequent disruption in these protein functions will lead to aneurysm development." (PMID 37629506, 2023). "The disruption of the ECM via mutations in Exon 3 and Exon 4 of PRDM5 supports our hypothesis that these variations may contribute to a loss of vascular integrity, leading to subsequent aneurysm formation." (PMID 37629506, 2023). "Though the mechanism behind PRDM5 variant and subsequent aneurysm development is currently unknown, dysregulation in TGF-β signaling is an intriguing and potential mechanism due to its known role in aneurysm development." (PMID 38892036, 2024).
deafness (2 papers, 2013 to 2023). An inherited or acquired condition characterized by the complete loss of the ability to hear from one or both ears. "This is borne out by the identification of variable degrees of deafness in three of seven families with PRDM5-associated BCS, including all affected individuals in families BCS-001 and BCS-002 in which mutations were first identified." (PMID 23642083, 2013).
leukemia (2 papers, 2019 to 2021). A malignant (clonal) hematologic disorder, involving hematopoietic stem cells and characterized by the presence of primitive or atypical myeloid or lymphoid cells in the bone marrow and the blood. "Moreover, we revealed that PRDM5 overexpression dramatically promoted leukemia cell growth and proliferation in vivo." (PMID 31119897, 2019). "Due to the distinct proliferation‐promoting effects of PRDM5 overexpression in leukemia cells observed in vitro, we then examined whether overexpression of PRDM5 affects the oncogenic capacity of AML cells in vivo." (PMID 31119897, 2019).
adenoma (1 paper, 2015). A neoplasm arising from the epithelium. "Additionally, PRDM5 loss resulted in increased adenoma burden in mice models that had a deregulated Wnt pathway background." (PMID 25613750, 2015). "Cancer (214 BRAF mutant, 122 BRAF wild type) and polyp (59 serrated polyps, 40 conventional adenomas) cohorts were analysed for PRDM5 promoter methylation using MethyLight technology." (PMID 25613750, 2015). "The absence of PRDM5 methylation found in conventional adenomas and the low rate seen in BRAF wild type cancers indicates that PRDM5 methylation is not an important event in traditional pathway cancers." (PMID 25613750, 2015).
aneurysmal disease (1 paper, 2023). "Among all patients with aneurysmal disease who underwent clinical genetic screening in our program (N = 145), two patients were found to have variants of uncertain significance (VUS) in the PRDM5 gene." (PMID 37629506, 2023).
cardiomyopathy (1 paper, 2025). A disease of the heart muscle or myocardium proper. "This is particularly pertinent in genes with variable penetrance or dual-phenotypic overlap, such as FLNA (neurovascular/cardiac), DSP (aortic/cardiomyopathy), or PRDM5 (ocular/aortic)." (PMID 40981152, 2025).
corneal dystrophy (1 paper, 2024). The term corneal dystrophy embraces a heterogeneous group of bilateral genetically determined non-inflammatory corneal diseases that are usually restricted to the cornea. "The heterozygous c.26G>A/p.Arg9Lys of PRDM5 was identified only in a patient diagnosed with corneal dystrophy (Case jh3)." (PMID 38785568, 2024).
Ehlers-Danlos syndrome (1 paper, 2012). The Ehlers–Danlos syndromes (EDS) are a clinically and genetically heterogeneous group of heritable connective tissue disorders (HCTDs) characterized by joint hypermobility, skin hyperextensibility, and tissue fragility. "The distinct expression pattern observed for Prdm5 in developing skeleton prompted us to evaluate a bone phenotype but future studies will be needed to understand if Prdm5LacZ/LacZ mice develop also corneal, skin and joint defects resembling BCS or related diseases such as Ehlers-Danlos syndrome." (PMID 22589746, 2012).
esophageal cancer (1 paper, 2022). A primary or metastatic malignant neoplasm involving the esophagus. "Whether esophageal cancer patients with high PRDM5 expression can enhance the efficacy of PD-1 inhibitors by affecting the corresponding immune cells will be worthy of our further study." (PMID 35799142, 2022).
esophageal squamous cell carcinoma (1 paper, 2022). Esophageal squamous cell carcinoma (ESCC) is a type of esophageal carcinoma (EC) that can affect any part of the esophagus, but is usually located in the upper or middle third. "In the future, more detailed studies are still needed to describe and reveal the underlying mechanism of PRDM5 multiple pathological functions in esophageal squamous cell carcinoma." (PMID 35799142, 2022). "As a tumor suppressor gene in esophageal squamous cell carcinoma, PRDM5 can be used as a biomarker to predict the survival of patients with esophageal squamous cell carcinoma, and the high expression level of PRDM5 is associated with longer OS in patients who underwent postoperative therapy." (PMID 35799142, 2022). "In present study, expression of PRDM5 mRNA in esophageal squamous cell carcinoma patients was conducted using the Cancer Genome Atlas (TCGA) and Gene Expression Omnibus (GEO) database." (PMID 35799142, 2022). "Based on the TCGA database, patients of Esophageal squamous cell carcinoma with high PRDM5 mRNA levels displayed longer OS than those with low expression (P = 0.0254)." (PMID 35799142, 2022). "This study investigated the relationship between PRDM5 expression and survival outcome in esophageal squamous cell carcinoma and explored the mechanism in tumor development." (PMID 35799142, 2022). "A comprehensive understanding of the multiple roles of PRDM5 in esophageal squamous cell carcinoma will provide more important clinical value for PRDM5 as a diagnostic indicator, prognostic marker and treatment target for clinical treatment." (PMID 35799142, 2022). "Furthermore, it was also shown that PRDM5 expression was lower in poorly differentiated esophageal squamous cell carcinoma and on the contrary in highly differentiated esophageal squamous cell carcinoma." (PMID 35799142, 2022). "The methylation of PRDM5 may be involved in the early events of esophageal squamous cell carcinoma, such as esophagitis." (PMID 35799142, 2022). "However, postoperative adjuvant treatment for patients with stage I-II Esophageal squamous cell carcinoma after surgery has little benefit on OS, the results also suggested that postoperative adjuvant treatment for patients with high expression of PRDM5 can help to prolong DFS and OS." (PMID 35799142, 2022). "The TCGA database and GEO database show that PRDM5 mRNA level in esophageal squamous cell carcinoma adjacent tissues was higher than that of cancer tissues, and ESCC patients with high expression of PRDM5 mRNA had better overall survival." (PMID 35799142, 2022). "We then performed methylation PCR on eight pairs of Esophageal squamous cell carcinoma tissue and found that PRDM5 DNA was highly methylated in cancer tissues, and absent in adjacent tissues." (PMID 35799142, 2022). "Based on this research, we found that the expression of PRDM5 in esophageal para-tumor tissue was significantly higher than in tumor tissues, regardless of mRNA level or protein level, and esophageal squamous cell carcinoma patients with high expression of PRDM5 had a better prognosis." (PMID 35799142, 2022). "Furthermore, PRDM5 expression in esophageal squamous cell carcinoma cells may affect WNT/β-catenin signaling pathways, which further affect the esophageal squamous cell carcinoma cell proliferation, migration, and invasion capacity." (PMID 35799142, 2022). "The role of the PRDM5 in esophageal squamous cell carcinoma (ESCC) has not been revealed." (PMID 35799142, 2022). "Our previous results confirmed that the expression level of PRDM5 is related to the pathological characteristics of tumor size, then we speculate whether the expression of PRDM5 affected CDK4 and thus affected the proliferation ability of esophageal squamous cell carcinoma cells." (PMID 35799142, 2022).
esophageal tumor (1 paper, 2022). "From TCGA database and GSE53622, GSE53624 two data sets, it was found that PRDM5 mRNA level in esophageal tumor tissue was significantly lower than para-tumor tissue." (PMID 35799142, 2022). "Next, the expression of PRDM5 of esophageal tumor tissues and paired para-tumor tissues were analyzed." (PMID 35799142, 2022). "It was found that the expression of PRDM5 was lower in 15 specimens of esophageal tumor than para-tumor tissues." (PMID 35799142, 2022). "Taken together, this work uncovers PRDM5 is a negative prognostic factor in esophageal tumor cell." (PMID 35799142, 2022).
hepatocellular carcinoma (1 paper, 2011). A malignant tumor that arises from hepatocytes. "MSP detected PRDM5 methylation in 93% (43/46) nasopharyngeal, 58% (25/43) esophageal, 88% (37/42) gastric and 63% (29/46) hepatocellular carcinomas." (PMID 22087297, 2011).
lung adenocarcinoma (1 paper, 2023). A carcinoma that arises from the lung and is characterized by the presence of malignant glandular epithelial cells. "Consistent with the results above, Kaplan–Meier survival analysis showed that lower PRDM5 expression was associated with a poorer survival rate in lung adenocarcinoma patients." (PMID 36127737, 2023). "We observed deregulated PRDM5 in several lung adenocarcinoma cell lines and its association with a poor prognosis." (PMID 36127737, 2023). "Reduced PRDM5 expression was observed in lung adenocarcinoma cells when compared with BEAS‐2B cells." (PMID 36127737, 2023). "PRDM5 overexpression inhibited the proliferation of lung adenocarcinoma cells in vitro and suppressed tumor growth in a xenograft model." (PMID 36127737, 2023). "Our study suggests that deregulation of PRDM5 promotes the proliferation of lung adenocarcinoma cells by downregulating SOCS1 and then upregulating the JAK2/STAT3 signaling pathway." (PMID 36127737, 2023). "Taken together, the results demonstrated that deregulation of PRDM5 gave rise to increased cell proliferation in lung adenocarcinoma cells." (PMID 36127737, 2023). "Our study suggests that the low expression of PRDM5 promotes the proliferation of lung adenocarcinoma cells by downregulating SOCS1 and then upregulating the JAK2/STAT3 signaling pathway." (PMID 36127737, 2023). "PRDM5 repression in lung adenocarcinoma cell lines suppressed the expression of SOCS1, thereby regulating downstream signaling pathways or target proteins." (PMID 36127737, 2023). "High‐throughput screening of 58 tumor‐normal paired lung adenocarcinoma (LUAD) samples revealed that PRDM5 expression in adenocarcinoma tissues was lower than that in para‐carcinoma tissues." (PMID 36127737, 2023). "To identify the PRDM5 expression profiles in lung adenocarcinoma, we examined the expression status of PRDM5 in several lung adenocarcinoma cell lines and immortalized human bronchial epithelial BEAS‐2B cells." (PMID 36127737, 2023). "The results above indicated that inhibition of the JAK2/STAT3 pathway triggered by SOCS1 might be mediated by PRDM5 in lung adenocarcinoma cells." (PMID 36127737, 2023). "Moreover, overexpression of PRDM5 suppressed both orthotopic tumor growth in vivo and cell proliferation in vitro, indicating its tumor suppressive property in lung adenocarcinoma." (PMID 36127737, 2023). "In summary, our study suggests that PRDM5 functions as a tumor suppressor in lung adenocarcinoma." (PMID 36127737, 2023). "To investigate the potential mechanism by which PRDM5 deregulation promoted the proliferation of lung adenocarcinoma cells, we tested the expression levels of components of the JAK2/STAT3 pathway in A549 cells overexpressing PRDM5." (PMID 36127737, 2023). "Although previous study showed that overexpression of PRDM5 led to G2/M arrest and apoptosis of tumor cells, we failed to acquire consistent results in lung adenocarcinoma cell lines." (PMID 36127737, 2023). "According to our results, overexpressed PRDM5 is likely to upregulate the promoter activity of SOCS1 and further suppress the JAK2/STAT3 pathway by inhibiting the phosphorylation of JAK2 and STAT3, thus repressing cell proliferation in lung adenocarcinoma." (PMID 36127737, 2023). "After analyzing the data of PRDM5 expression in human lung samples (GEO: GSE40791), we observed decreased mRNA levels of PRDM5 in lung adenocarcinoma tissues compared with normal lung tissues, which was in accord with the results from the BEAS‐2B cells and lung adenocarcinoma cell lines." (PMID 36127737, 2023).
myopia (1 paper, 2015). "PRDM5 mutations may further contribute to weaknesses at the level of Bruch’s membrane caused by myopia, a hypothesis consistent with our immunohistochemical results, although IHC was only performed on two patients with a PRDM5 Δ9-14, which results in the production of a truncated protein product." (PMID 26560304, 2015). "We also report abnormal expression of ECM components in fibroblasts from a BCS patient with high axial myopia and choroidal neovascularization carrying a novel p.Glu134* mutation in PRDM5, a patient who had not sustained a corneal rupture." (PMID 26560304, 2015).